ZNF768 (zinc finger protein 768)
Diseases named in the same sentence as ZNF768 in open-access papers (continued):
Sharing a sentence is not in itself a finding about the gene and the disease.
cancer (continued). "Cancer genomics and immunohistochemical analyses reveal that ZNF768 is often amplified and/or overexpressed in tumors, suggesting that cells could use ZNF768 to bypass senescence, sustain proliferation and promote malignant transformation." (PMID 34404770, 2021). "In cancer cell lines, ZNF768 promotes the expression of key genes required for proliferation." (PMID 34439288, 2021). "Despite evidence that ZNF768 is overexpressed in NSCLC, the exact role of ZNF768 in cancer and its clinicopathological relevance remain unknown." (PMID 34439288, 2021). "Because ZNF768 is rarely amplified or overexpressed in lung tumors, these results indicate that post-transcriptional and/or post-translational processes likely take place to enforce ZNF768 protein expression in cancer." (PMID 34404770, 2021). "Based on cancer genomic databases, we found that ZNF768 overexpression is common in a variety of human cancers suggesting that elevated levels of ZNF768 could serve as a way to bypass oncogene-induced senescence and sustain tumor proliferation." (PMID 34439288, 2021). "Owing to the importance of ZNF768 in supporting cell proliferation, we next sought to define whether ZNF768 gene is altered or its expression modulated in human cancers." (PMID 34404770, 2021). "Although additional studies are needed to define the precise contribution of ZNF768 to human cancer, these observations suggest that cells might use ZNF768 to sustain proliferation, bypass senescence and promote malignant transformation." (PMID 34404770, 2021). "Additional studies will be needed to define the role of ZNF768 in human cancer." (PMID 34404770, 2021). "Testing these hypotheses could help define the exact functions of ZNF768 in cancer and explore its therapeutic potential in this disease." (PMID 34439288, 2021). "The use of animal models of cancer such as LUAD driven by oncogene(s) or xenografts with altered levels of ZNF768 could establish whether ZNF768 directly contributes to tumor formation in vivo." (PMID 34439288, 2021). "Furthermore, several lines of evidence suggest that ZNF768 may promote cancer cell proliferation and tumor development." (PMID 40473701, 2025). "Expanding these studies to additional cancer mouse models, different strain backgrounds with higher oncogenic potential, and broader tumor characteristics may reveal novel functions or impacts of ZNF768 overexpression on tumorigenesis." (PMID 40473701, 2025). "Thus, elevated ZNF768 levels might be more common in tumors than predicted from cancer genomics and transcriptomics analyses." (PMID 34404770, 2021). "Zinc finger protein 768 (ZNF768) was recently identified as a novel transcription factor controlling cell fate decision and proliferation in normal and cancer cells in vitro." (PMID 40133474, 2025). "ZNF768 is a protein that contains C2H2 domains in its C-terminal section and localizes to the nucleus in cancer cell lines." (PMID 34439288, 2021). "Zinc-finger protein 768 (ZNF768) is a transcription factor that has been shown to greatly impact the proliferation and the survival of cancer cells in vitro." (PMID 34439288, 2021). "Cancer genomics and immunohistochemical analyses revealed that ZNF768 is frequently amplified and/or overexpressed in various human malignancies, suggesting that ZNF768 could contribute to the bypass of cellular senescence and to the promotion of oncogene-induced transformation." (PMID 34404770, 2021). "Overall, these observations indicate that a disconnection between ZNF768 mRNA expression and ZNF768 protein levels exists in LUAD, and that measuring ZNF768 protein levels is key to study this transcription factor in this cancer." (PMID 34439288, 2021).
cancer (continued). "Secondly, while in vitro evidence and cancer proteomics point to a possible role of ZNF768 in LUAD, additional studies are needed to define the exact contribution of ZNF768 in tumorigenesis." (PMID 34439288, 2021). "We also show that forcing ZNF768 expression is not sufficient to promote tumor development in carcinogen- and oncogene-driven cancer mouse models." (PMID 40473701, 2025). "With this work, we provide the scientific community a versatile model to study ZNF768 in vivo, and we reveal that ZNF768 is not a primary driver of cancer in mice." (PMID 40473701, 2025). "We show that whole-body ZNF768 overexpression does not impact mouse physiology and is not sufficient to promote tumor development in carcinogen- and oncogene-driven cancer mouse models." (PMID 40473701, 2025). "Despite having observed high levels of ZNF768 in LUAD and in certain types of cancer, the exact functions of ZNF768 in cancer remain unknown." (PMID 34439288, 2021). "Hence, the lack of an association between ZNF768 and prognosis in LUAD does not detract from its association with proliferation in this cancer and its possible contribution to tumorigenesis." (PMID 34439288, 2021). "Second, these cancer types do not show severe changes in ZNF768 mRNA levels." (PMID 34404770, 2021). "Autoantibodies to ZNF768 were detected in sera of 15 out of 96 CRC patients (15.6%) and were absent in non-cancer controls (0/35)." (PMID 25875936, 2015).
tumor (4 papers, 2021 to 2025). "To explore the oncogenic potential of ZNF768, we assessed spontaneous tumor susceptibility in control and WB-ZNF768-Tg during a period of 20 months." (PMID 40473701, 2025). "Altogether, these results support previous observations in cells and reveal a functional impact of ZNF768 loss on tumour development in vivo." (PMID 40473701, 2025). "However, ZNF768 possibly associates with tumor stage in LUAD with a p-value just above the alpha in our cohort and higher levels of ZNF768 in tumors of stage 3 and above." (PMID 34439288, 2021). "To test this hypothesis, we measured the impact of ZNF768 loss on tumor development in mice." (PMID 40133474, 2025). "We also found a tendency for reduced tumor grade in mice depleted from ZNF768, supporting the idea that ZNF768 exerts pro-oncogenic functions, at least in LUAD." (PMID 40133474, 2025). "With the median being 90 in our cohort, this result highlights the fact that most tumor cells in LUAD express ZNF768." (PMID 34439288, 2021). "Although ZNF768 was expressed at high levels in these mice, the use of homozygous FLExZnf768 mice showing even higher ZNF768 expression might have been required to impact tumor development." (PMID 40473701, 2025). "Although these results suggest that ZNF768 per se is insufficient to drive tumour development in mice, it is possible that adaptive mechanisms might have been triggered to counteract the effect of ZNF768 overexpression." (PMID 40473701, 2025). "Although ZNF768 loss did not induce gross changes in tumor morphology, we observed that ZNF768 null tumors had increased levels of CDKN1A (p21)." (PMID 40133474, 2025). "Over this time, we observed no spontaneous tumors in WB-ZNF768-Tg mice, indicating that sustained ZNF768 overexpression is not sufficient to initiate and promote tumor development in mice." (PMID 40473701, 2025). "Overall, we report the generation of a conditional mouse for ZNF768 overexpression and reveal that forcing ZNF768 expression is not sufficient to alter tumour development in mice." (PMID 40473701, 2025).
ZNF768 also shares sentences with these, for which no sentence is quoted: adrenocortical carcinoma (2 papers); cholangiocarcinoma (2); diffuse large B-cell lymphoma (2); glioma (2); lung adenocarcinoma (2); pancreatic adenocarcinoma (2); thymoma (2); bladder urothelial carcinoma (1); breast invasive carcinoma (1); endometrial carcinoma (1); kidney chromophobe carcinoma (1); lung squamous cell carcinomas (1); mature B-cell neoplasm (1); melanoma (1); testicular germ cell tumor (1).